PTPN18 (protein tyrosine phosphatase non-receptor type 18)
Description:
Differentially dephosphorylate autophosphorylated tyrosine kinases which are known to be overexpressed in tumor tissues.
Synonyms: BDP1; PTP-HSCF
Tractability: PROTAC: its protein half-life has been measured.
Target class: Tyrosine protein phosphatase; Enzyme; Phosphatase; Protein Phosphatase
Gene: Protein-coding gene on chromosome 2 (130,356,027 to 130,375,405, forward strand). Ensembl gene ENSG00000072135.
Subcellular location: Nucleus; Cytoplasm
Subcellular location (Human Protein Atlas): Intermediate filaments
Pathways (Reactome):
Immune System: Interleukin-37 signaling
Signal Transduction: Downregulation of ERBB2 signaling
Gene Ontology:
Molecular function: protein binding; protein tyrosine phosphatase activity; non-membrane spanning protein tyrosine phosphatase activity; phosphoprotein phosphatase activity
Biological process: negative regulation of ERBB signaling pathway; protein dephosphorylation
Cellular component: cytoplasm; cytosol; nucleoplasm; nucleus
Genetic constraint (gnomAD): Loss-of-function variants: 65 observed, 66.11 expected, observed/expected ratio (o/e) 0.98, 90% interval 0.8 to 1.21. The upper end of that interval is the gene's LOEUF score, 1.21, which puts it in group 5 of 6, group 1 being the genes least tolerant of losing a copy. Missense variants: 614 observed, 589.13 expected, observed/expected ratio (o/e) 1.04, 90% interval 0.98 to 1.11. Synonymous variants: 255 observed, 237.84 expected, observed/expected ratio (o/e) 1.07, 90% interval 0.97 to 1.19.
Homologues: Orthologues: chimpanzee PTPN18 (97% identical), macaque PTPN18 (95% identical), pig PTPN18 (83% identical), mouse Ptpn18 (75% identical), rat Ptpn18 (75% identical), guinea pig PTPN18 (73% identical), rabbit PTPN18 (70% identical). Paralogues in human: PTPN22 (37% identical), PTPN12 (37% identical), PTPRF (25% identical), PTPRM (25% identical), PTPRS (25% identical), PTPRD (24% identical), PTPRG (24% identical), PTPRH (24% identical), PTPRT (23% identical), PTPRZ1 (23% identical), PTPRN2 (23% identical), PTPRK (23% identical), and 23 more.
Diseases named in the same sentence as PTPN18 in open-access papers:
PTPN18 is named in the same sentence as 17 diseases in open-access papers, as found by Europe PMC text mining. Sharing a sentence is not in itself a finding about the gene and the disease. The quoted sentences say what the papers report.
endometrial cancer (8 papers, 2021 to 2023). Primary or metastatic malignant neoplasm involving the endometrium (mucous membrane that lines the endometrial cavity). "Some studies reported that overexpression of PTPN18 promotes the cell growth and tumorigenesis of colorectal cancer and accelerates endometrial cancer cell line proliferation and metastasis." (PMID 36846716, 2023). "A study also demonstrated that PTPN18 promotes endometrial cancer cell line proliferation and metastasis but inhibits their apoptosis." (PMID 36846716, 2023). "PTPN18 expression is upregulated in endometrial cancer and inhibited ferroptosis by upregulating the activity of GPX4/xCT, thus promoting the growth of endometrial cancer cells." (PMID 35775079, 2022). "We found that PTPN18 was localized in both the nucleus and cytoplasm in breast cancer rather than accumulated exclusively in the cytoplasm, as found in colorectal and endometrial cancers." (PMID 35982039, 2022). "Uniquely, silencing of PTPN18 induced ferroptosis in endometrial cancer cells through p-P38-mediated GPX4/xCT downregulation, while downregulation of PTPN18 can inhibit proliferation and metastasis and promote apoptosis of endometrial cancer." (PMID 35328170, 2022). "Previous studies have revealed that PTPN18 prevents tumor progression in breast and hepatocellular cancers but promotes the development of colorectal and endometrial cancer." (PMID 35982039, 2022). "PTPN18 is considered to serve as an oncogene in endometrial cancer, which promotes proliferation and metastasis of endometrial cancer cells." (PMID 34922551, 2021). "Likewise, PTPN18 promotes proliferation and metastasis and restrains apoptosis in endometrial cancer." (PMID 35957898, 2022). "Mechanistically, silencing of PTPN18 induced ferroptosis in endometrial cancer cells by increasing intracellular reactive oxygen species (ROS) levels and p-p38 expression as well as decreasing the expression of glutathione peroxidase 4 (GPX4) and system xc(-) cystine/glutamate antiporter (xCT)." (PMID 35957898, 2022). "Recent studies have shown that knocking down PTPN18 may inhibit tumor proliferation in endometrial cancer and stimulate cell apoptosis." (PMID 35154122, 2022). "Another study revealed that silencing of PTPN18 could induce ferroptosis by inhibiting GPX4 activity, leading to the suppression of endometrial cancer cell growth." (PMID 34922551, 2021).
breast carcinoma (4 papers, 2022 to 2026). "PTPN18 was inversely associated with distant metastasis, lung metastasis, and poor prognosis in breast cancer." (PMID 35982039, 2022). "PTPN18 has been described to be expressed in breast cancer cells and implicated in diverse cellular functions, such as regulation of HER2 signaling, dynamic rearrangements of the cytoskeleton, and activation of the MYC-CDK4 axis." (PMID 35982039, 2022). "In keeping with the clinical data and human tissue analyses, PTPN18 expression was negatively associated with metastatic capacity in multiple breast cancer cell lines." (PMID 35982039, 2022). "This study demonstrates that the protein tyrosine phosphatase PTPN18 is downregulated in metastatic breast cancer tissues and is associated with better metastasis-free survival." (PMID 35982039, 2022). "PTPN18 is downregulated in metastatic breast cancer tissue and predicts lung metastasis-free survival in patients with breast cancer." (PMID 35982039, 2022). "To further evaluate the interaction between PTPN18 and importin α/β, we detected the expression of importin genes in breast cancer and used immunoprecipitation to test their binding to PTPN18." (PMID 35982039, 2022). "Adding to our finding that ectopic expression of PTPN18 resulted in dephosphorylation of ETS1 and promoted its degradation, we further delineated the role of nuclear PTPN18 in regulating breast cancer metastasis by gain/loss-of-function experiments." (PMID 35982039, 2022). "Overall, these results support the idea that MVP and importin β2 cooperatively promote PTPN18 translocation from the cytoplasm to the nucleus in breast cancer cells." (PMID 35982039, 2022). "As expected, nuclear PTPN18 inhibited the expression of TGFβ1-regulated genes in breast cancer cells, and the suppressive role of nuclear PTPN18 in cell migration was validated by Transwell assays and wound healing assays in multiple breast cancer cell lines." (PMID 35982039, 2022). "In order to fully reflect the whole pathway, we applied the MVP EA/TA mutant to prevent PTPN18 nuclear import and confirmed the role of nuclear PTPN18 in regulating breast cancer metastasis." (PMID 35982039, 2022). "Our data highlight PTPN18 as a suppressor of breast cancer metastasis and provide an effective antimetastatic therapeutic strategy." (PMID 35982039, 2022). "While these studies established PTPN18 as a suppressive regulator of breast cancer progression, the molecular mechanism of PTPN18 in breast cancer metastasis remains to be clarified." (PMID 35982039, 2022). "We sought to identify the primary interaction partners of PTPN18 in breast cancer cells and explore its novel molecular functions." (PMID 35982039, 2022). "Given that metastasis is the main contributor to breast cancer mortality and considering the suppressive role of PTPN18 in breast cancer, we explored the exact function of PTPN18 in breast cancer metastasis." (PMID 35982039, 2022). "Ectopic expression of PTPN18 inhibits breast cancer cell metastasis." (PMID 35982039, 2022). "In addition to the well-established role of PTPN18 in breast cancer, our previous study found that PTPN18 and CSK cooperate to inhibit the events triggered by SRC kinases." (PMID 35982039, 2022). "Nuclear import of PTPN18 inhibited breast cancer metastasis mediated by MVP and importin β2." (PMID 36556168, 2022). "PTPN18 localizes in both the nucleus and cytoplasm in breast cancer cells." (PMID 35982039, 2022). "Notably, downregulation of PTPN18 has frequently been detected in metastatic breast cancer tissues." (PMID 35982039, 2022). "As a result, the interaction between PTPN18 and FBL affects the proliferation and apoptosis of breast cancer cells, thus inhibiting tumor growth." (PMID 41559020, 2026). "PTPN18 WT decreased ETS1 stability and inhibited breast cancer metastasis, but two cytoplasmic PTPN18 mutants, mC-NLS and mPY-NLS, stabilized ETS1 and restored the metastatic ability by spatiotemporal regulation." (PMID 35982039, 2022).
breast carcinoma (continued). "PTPN18 (also called PTP-HSCF or BDP1), a member of the protein tyrosine phosphatase superfamily, has been reported to be a tumor suppressor in breast cancer by dephosphorylating HER2 and suppressing cell proliferation and invasion." (PMID 35982039, 2022). "Therefore, this event may represent one of the driving forces for early-stage breast tumor cells to undergo EMT and subsequent metastatic progression, thus highlighting the role of PTPN18 as a potential target for early therapeutic intervention in breast cancer progression." (PMID 35982039, 2022). "Consistent with our finding that the PY-NLS/importin β2 nuclear transport system regulates PTPN18 nuclear localization in the presence of MVP, we established that knockdown of importin β2 or MVP prevents PTPN18 nuclear accumulation in breast cancer." (PMID 35982039, 2022). "PTPN18 (Protein Tyrosine Phosphatase Non-Receptor Type 18) is a suppressor of breast cancer metastasis, thereby providing a potential effective antimetastatic therapeutic strategy." (PMID 41009751, 2025). "In addition, nuclear PTPN18 inhibited TGFβ signaling-regulated EMT and reduced the metastatic ability of breast cancer cells." (PMID 35982039, 2022). "Indeed, significant correlations between PTPN18 and EMT-related genes were observed in breast cancer cell lines." (PMID 35982039, 2022). "PTPN18 is translocated from the cytoplasm to the nucleus by MVP and importin β2 in breast cancer." (PMID 35982039, 2022). "Interestingly, PTPN18 was not significantly different in primary breast cancer tissues with and without metastasis." (PMID 35982039, 2022). "Together, these data implied that nuclear PTPN18 but not cytoplasmic PTPN18 antagonizes TGFβ signaling-regulated EMT and reduces the metastatic ability of breast cancer cells." (PMID 35982039, 2022). "Our extensive analysis of PTPN18 in EMT and metastasis indicated that nuclear PTPN18 but not cytoplasmic PTPN18 antagonized TGFβ signaling-regulated EMT and reduced the metastatic ability of breast cancer cells through regulation of ETS1 phosphorylation in breast cancer." (PMID 35982039, 2022).
colorectal cancer (2 papers, 2022 to 2023). A primary or metastatic malignant neoplasm that affects the colon or rectum. "Ectopic expression of PTPN18 facilitates cell growth and tumorigenesis of colorectal cancer." (PMID 36846716, 2023). "PTPN18 triggers MYC signaling by interacting with MYC and increases CDK4 protein expression in colorectal cancer." (PMID 36846716, 2023). "PTPN18 activates myelocytomatosis oncogene (MYC) signaling pathway and further potentiates cyclin-dependent kinase 4 (CDK4) expression to promote colorectal cancer progression." (PMID 35957898, 2022). "In colorectal cancer, PTPN1, PTPN2 and PTPN18 undoubtedly drive its progression." (PMID 35957898, 2022).
glioblastoma (2 papers, 2023 to 2024). The most malignant astrocytic tumor (WHO grade IV). "We explored the association of the expression of PTPN18 with clinicopathological parameters and prognostic value to present more perspectives on the pathologic role of PTPN18 in glioblastoma progression." (PMID 36846716, 2023). "Our results showed that patients with higher PTPN18 expression have an advanced grade and correlate with the poor OS of glioblastoma." (PMID 36846716, 2023). "In this study, we demonstrated the upregulation of PTPN18 in glioblastoma compared with normal tissue from TCGA and other independent datasets, which were validated using human specimens at the protein level." (PMID 36846716, 2023). "To further elucidate the role of PTPN18 on glioblastoma progression, we evaluated the immune cell infiltration in C57BL/6 mice." (PMID 36846716, 2023). "Functional experiments showed that ectopic PTPN18 promoted cell proliferation, colony formation, and tumor growth in nude mice, indicating the potential oncogenic role of PTPN18 in glioblastoma." (PMID 36846716, 2023). "In the present study, we explored the role of PTPN18 in glioblastoma progression with immune response." (PMID 36846716, 2023). "We systematically analyzed the expression patterns, predictive values, and immunological characteristics of PTPN18 in glioblastoma." (PMID 36846716, 2023). "Together, these data indicated that PTPN18 instigates glioblastoma progression by enhancing immunosuppression." (PMID 36846716, 2023). "Our results illustrate the characterization of PTPN18 in glioblastoma and highlight the potential value as an immunotherapeutic target for glioblastoma treatment." (PMID 36846716, 2023). "We, therefore, analyzed the correlation between the expression of PTPN18 and the infiltration of 25 immune cells in glioblastoma and validated the results using immunohistochemistry." (PMID 36846716, 2023). "Our data revealed that PTPN18 exhibits potential cancerogenic properties in glioblastoma with a poor prognosis." (PMID 36846716, 2023). "Our data showed that PTPN18 is potentially cancerogenic in glioblastoma with advanced grades and poor prognosis." (PMID 36846716, 2023). "Of these, PTPN18 overexpression is particularly noteworthy as this gene has been shown to promote glioblastomas by decreasing CD8+ T cell infiltration to enhance immune suppression, making the identification of immunotherapy targets for this gene crucial for halting tumor growth." (PMID 39796063, 2024). "To further address whether PTPN18 was correlated with glioma tumorigenesis, we performed enrichment analyses of PTPN18 in glioblastoma." (PMID 36846716, 2023). "Together, these results suggest that PTPN18 is a potential oncogene in glioblastoma and may be a promising target for glioblastoma treatment." (PMID 36846716, 2023). "In addition, PTPN18 facilitates glioblastoma progression by accelerating glioma cell prefiltration, colony formation, and tumor growth in mice." (PMID 36846716, 2023). "However, to our knowledge, the information regarding the effect of PTPN18 on glioblastoma progression is limited." (PMID 36846716, 2023). "Overall, our results showed that the upregulation of PTPN18 in glioblastoma might effectively predict clinical prognosis." (PMID 36846716, 2023). "Moreover, PTPN18 significantly correlated with tumor progression and poor survival, indicating the potential cancerogenic properties of glioblastoma." (PMID 36846716, 2023). "Therefore, we hypothesized that increased expression of PTPN18 led to glioblastoma progression by decreasing the infiltration of CD8+ T cells." (PMID 36846716, 2023). "Moreover, this study demonstrated that the effect and mechanism of PTPN18 on promoting glioblastoma are mediated by reducing immune infiltration and enhancing immune suppression, indicating the potential value of targeting PTPN18 as an immunotherapy strategy for glioblastoma." (PMID 36846716, 2023).
glioblastoma (continued). "High expression of PTPN18 correlated with CD8+ T cell exhaustion and immune suppression in glioblastoma." (PMID 36846716, 2023). "However, the potential functions and mechanisms of PTPN18 in glioblastoma remain unclear." (PMID 36846716, 2023). "Mechanistically, PTPN18 positively correlates with immune suppression and CD8+ T cell exhaustion and promotes glioblastoma progression by regulating the cell cycle and apoptosis." (PMID 36846716, 2023). "We further estimated the association of PTPN18 expression with immune infiltration and found that higher expression of PTPN18 correlated with reduced CD8+ T cells and poor prognosis in glioblastoma." (PMID 36846716, 2023).
glioma (1 paper, 2023). A benign or malignant brain and spinal cord tumor that arises from glial cells (astrocytes, oligodendrocytes, ependymal cells). "To better address whether PTPN18 was correlated with glioma tumorigenesis, we analyzed the genomic alterations of PTPN18 and found that PTPN18 presented low mutational frequency across cancers with widespread CNV alterations." (PMID 36846716, 2023). "We also found that the expression of PTPN18 was significantly correlated with the stratification of glioma." (PMID 36846716, 2023). "PTPN18 was additionally expressed in various cancer cell lines, including glioma cell lines, according to the bulk data from the CCLE and GDSC datasets." (PMID 36846716, 2023). "We further applied clinical specimens and observed that PTPN18 was significantly overexpressed in glioma samples contrasted with the paired adjacent samples at the protein level." (PMID 36846716, 2023). "We found that the overexpression of PTPN18 notably enhanced the growth velocity in different glioma cell lines, while PTPN18 silencing inhibited cell growth." (PMID 36846716, 2023). "PTPN18 was associated with worse survival in LGG and GBM from TCGA and three independent glioma datasets." (PMID 36846716, 2023). "Consistent with the GSEA results, PTPN18 was involved in anticancer immune response, which may advance the immunosuppressive microenvironment of glioma, as a clear example of inflammation-related cancer." (PMID 36846716, 2023). "The upregulation of PTPN18 was further validated in three independent glioma datasets." (PMID 36846716, 2023). "We therefore performed cell cycle and apoptosis analysis on PTPN18 in glioma cells." (PMID 36846716, 2023). "Together, PTPN18 may be a promising target for attenuating tumor immunosuppression for glioma treatment." (PMID 36846716, 2023). "We observed that PTPN18 expression was positively correlated with six immunosuppressive genes (PD-L1, PD-1, CTLA4, LAG3, HAVCR2, and CD244) in most cancers, including glioma." (PMID 36846716, 2023).
ischemic stroke (1 paper, 2025). A stroke disorder caused by obstruction of blood flow to the brain, due to thrombotic (local blood clot formation) or embolic (due to a blood clot or other material traveling from another site) event. "Among them, FTH1, SLC40A1, NRAS, CD82, and PTPN18 emerged as potential key targets underlying the antiferroptotic effects of acupuncture on ischemic stroke." (PMID 40552324, 2025). "Bioinformatics analysis and RT-qPCR suggested that FTH1, SLC40A1, NRAS, CD82, and PTPN18 might serve as potential key targets underlying the antiferroptotic effects of acupuncture on ischemic stroke." (PMID 40552324, 2025). "The results demonstrated that the expression levels of FTH1, SLC40A1, NRAS, CD82, CD44, and PTPN18 were upregulated in mice with ischemic stroke following acupuncture treatment." (PMID 40552324, 2025). "Moreover, FTH1, SLC40A1, NRAS, CD82, and PTPN18 levels significantly increased after acupuncture in ischemic stroke mice." (PMID 40552324, 2025). "Therefore, acupuncture may enhance the expression of PTPN18, thereby exerting inhibitory effects on ferroptosis in ischemic stroke." (PMID 40552324, 2025).
leukemia (1 paper, 2022). A malignant (clonal) hematologic disorder, involving hematopoietic stem cells and characterized by the presence of primitive or atypical myeloid or lymphoid cells in the bone marrow and the blood. "The findings showed that PTPN6, PTPN18, and PTPN22 had higher expression levels in leukemia than in normal blood samples, while PTPN1 had a lower expression level in the former than the latter." (PMID 36699453, 2022).